RHO (rhodopsin)
Diseases named in the same sentence as RHO in open-access papers (continued):
Sharing a sentence is not in itself a finding about the gene and the disease.
melanoma (12 papers, 2013 to 2025). A malignant, usually aggressive tumor composed of atypical, neoplastic melanocytes. "Melanoma cells can migrate by adopting different strategies; among them, rounded-amoeboid migration relies on high levels of RHO and RHO-associated protein kinase (ROCK) leading to high actomyosin contractility." (PMID 27308633, 2016). "For instance, rhodopsin and the triazolylpeptidyl penicillin derivative TAP7f suppress the Wnt/β-catenin signaling pathway, thereby reducing melanoma cell proliferation and migration." (PMID 40932870, 2025). "Several studies have shown the modulation of RHO GTPase expression and/or activity during adaptation to MAPKi and in MAPKi-resistant melanomas." (PMID 35159327, 2022). "Previous studies showed that NEDD9 functions as an adaptor protein to assemble protein complex containing Src and FAK for inhibition of RHO/ROCK signaling in order to promote mesenchymal invasion of NC-derived melanoma cells." (PMID 29084958, 2017). "It has been suggested that rhodopsin may impede the migration and invasion of melanoma B16F10 and A375 cells by inhibiting the Wnt/β-Catenin signaling pathway." (PMID 40932870, 2025). "Furthermore, rhodopsin also inhibits the growth of cancer cells by downregulating CD155 in melanoma B16F10 cells." (PMID 40932870, 2025). "Thus, we anticipated that SOX10 or high level of SOX9 regulates NEDD9 expression to promote melanoma migration through alteration of focal adhesion dynamics and RHO signaling activity." (PMID 30642390, 2019). "Furthermore, melanoma cells with high levels of RHO-ROCK-actomyosin have developed mechanisms to allow fast migration in physiological 3-dimensional (3D) environments and inhibit excessive RAC1-mediated cell adhesion." (PMID 27308633, 2016). "Generally, MAPKi-persistent and -resistant melanomas are more invasive and, with increased lung colonization ability, which is indicative of enhanced metastatic potential, providing further evidence of the involvement of RHO GTPase signalling and the actomyosin cytoskeleton in therapy resistance." (PMID 35159327, 2022). "Therefore, rhodopsin may be a potential drug for treating highly metastatic melanoma." (PMID 40932870, 2025). "Although the SMAD-dependent induction of RHO GEFs has been described in other studies, how TGFBR1 directly activates RHOA in melanoma cells in a SMAD-independent manner is unclear at present." (PMID 27835901, 2016). "Likewise, elevation of NEDD9 expression was detected in 30 to 50% of metastatic melanomas samples and promoted mesenchymal migration of melanoma cells through activation of RAC1 and inhibition of RHO/ROCK-driven amoeboid movement." (PMID 30642390, 2019). "RAC1 also affects 3D cell motility and inhibits RHO-ROCK signaling, further highlighting that the presence and high frequency of RAC1P29S in melanoma cases may have implications on both melanoma metastasis and survival in these patients." (PMID 30460237, 2018). "Increased ROS levels have been shown to effectively suppress RHO-ROCK mediated rounded-amoeboid invasion, but on the other hand an aged microenvironment induces ROS in melanoma cells, which creates slow-growing invasive tumours with increased potency to metastasise to the lung." (PMID 28380427, 2017). "However, both RHO GTPase arms cross-talk with pro-survival/proliferation signalling, given that RHOA-ROCK were shown to cooperate with pro-survival mediators (such as STAT3 and NF-κB in melanoma cells) while RAC1 activated PI3K-AKT in breast cancer cells." (PMID 35159327, 2022).
Cone rod dystrophy (11 papers, 2018 to 2025). "The “CRISPR-Cas9 model” is genetically representative of a common human rod-cone dystrophy as with this technique we specifically ablate a frequently mutated gene in rods by editing the Rhodopsin gene similar to the RHO mutation in human disease." (PMID 37531424, 2023). "The Prph2Y141C/+ represents a blended cone-rod dystrophy model, while the RhoP23H/+ is a rod-dominant disease (and rhodopsin is only expressed in rods) with cone loss occurring later, secondary to rod loss." (PMID 33138244, 2020). "The amino acid 88 may also have a structural role in rhodopsin because the human Leu-88 to Pro mutation leads to a severe early-onset rod-cone dystrophy phenotype in patients." (PMID 41282135, 2025). "A rhodopsin (RHO) mutation was found in 5 of 26 (19%) rod-cone dystrophy ODD patients." (PMID 33083048, 2020). "Progressive rod-cone degeneration (PRCD) is a photoreceptor outer segment (OS) disc-specific protein essential for maintaining OS structures while contributing to rhodopsin packaging densities and distribution in disc membranes." (PMID 36142714, 2022). "Here, we present the initial results of a pilot study targeting zebrafish orthologs of five human genes linked to RP: PDE6A, PDE6B, PDE6G, ABCA4, and RHO (note, ABCA4 is also linked to cone-rod dystrophy)." (PMID 30186835, 2018). "One with RHO-linked autosomal dominant (AD) RP will be re-reviewed and illustrated in further detail here, alongside a representative case of EYS-associated ARRP and even one with ABCA4-associated cone-rod dystrophy (CORD)." (PMID 37123408, 2023). "This is particularly relevant for the treatment of rod-cone dystrophies, which are highly prevalent in BBS and AS, as other visual GPCRs such as rhodopsin are trafficked via the BBSome across the connecting cilium to the outer segment of photoreceptor cells." (PMID 34365092, 2021).
glaucoma (8 papers, 2008 to 2025). Increased pressure in the eyeball due to obstruction of the outflow of aqueous humor. "Rhodopsin, the pigment present in rods, gives off toxic metabolites in RP, but cones are affected in late stages, so visual changes are noticed in advanced disease, much like in typical glaucoma with progressive peripheral vision loss." (PMID 41303269, 2025). "RHO has a close relationship with glaucoma, and the inhibition of RHO expression can lower intraocular pressure, change retinal vasculature perfusion, and promote regeneration of the optic nerve." (PMID 33299458, 2020). "However, an unexpected finding was that all opsin mRNAs from the outer retina (SW, MW opsins and rhodopsin) were significantly under expressed in case of experimental glaucoma (t-test, p<0.001)." (PMID 19079596, 2008).
retinoblastoma (8 papers, 2005 to 2025). A malignant tumor that originates in the nuclear layer of the retina. "Among the most upregulated genes were KRT5, KRT19, LCN2, SLP1 and S100A9, while GNAT1, PDE6G, WIF1, FRZB, and RHO were among the top downregulated genes in retinoblastoma." (PMID 40395327, 2025). "The highest agreement between RNA and protein level was observed for DDB2, CHAF1B, and POLD1, which were upregulated in retinoblastoma, and RHO, PDE6A, and CRABP1, which were downregulated." (PMID 40395327, 2025). "GSEA showed that the expression of the MRPL48 was correlated with Resolution of Sister Chromatid Cohesion, Mitotic Prometaphase, Retinoblastoma Gene in Cancer, RHO Gtpases Activate Formins, Mitotic Metaphase and Anaphase, and Cell Cycle Checkpoints." (PMID 38093387, 2023). "The significantly enriched pathways included Resolution of Sister Chromatid Cohesion, Mitotic Prometaphase, Retinoblastoma Gene in Cancer, RHO Gtpases Activate Formins, Mitotic Metaphase and Anaphase, and Cell Cycle Checkpoints." (PMID 38093387, 2023). "In DNAse I footprinting assays of the bovine rhodopsin proximal promoter, nuclear extracts from bovine retina and from Y79 and WERI retinoblastoma cells protected the BAT-1 (-103 to -84) site." (PMID 15963234, 2005).
diabetes (7 papers, 2012 to 2026). "Patient RP-0118 had early-onset RP and type 1 diabetes mellitus and carried the heterozygous variant p.(Arg132Trp) in RHO (MIM *300023), the most frequent gene in autosomal dominant RP; thus, he was reclassified to non-syndromic." (PMID 34448047, 2021). "One suggestion is that diabetes induces a more acidic condition within the rod photoreceptors that causes a delay in rhodopsin regeneration." (PMID 22355248, 2012). "A reduction of rhodopsin content has been reported in the rat model of DR at 4 mo after diabetes induction, along with a significant reduction in both scotopic and photopic amplitudes of the a- and b-waves of the electroretinogram (ERG) responses." (PMID 41266111, 2026). "Correlations have been found between diabetes and subnormal rhodopsin generation, reductions in the expression of genes involved with the phototransduction pathway, and with visual cycle protein levels." (PMID 22355248, 2012). "Interestingly, rod cell (stained with rhodopsin; green) morphology was similar between Akt2fl/fl and Akt2 cKO nondiabetic and diabetic mouse retinas (at a 2 month duration of diabetes)." (PMID 36229454, 2022). "It has been demonstrated that the retinas of rhodopsin knockout mice exhibit vascular attenuation in the capillary bed; however, in the retina of rhodopsin knockout mice with diabetes, it appears to have fewer vascular attenuation than that of nondiabetic counterparts." (PMID 28265339, 2017). "It is not yet clear how retinal oxidative stress (due to diabetes) and rhodopsin regeneration are mechanistically linked." (PMID 22355248, 2012). "To determine whether obesity-induced diabetes has any effect on the expression of PKM1, we immunostained the C57BLKS/J and db/db mouse retina sections with anti-PKM1 and anti-rhodopsin antibodies." (PMID 32366925, 2020).
myopia (7 papers, 2020 to 2025). "During dark adaptation, rhodopsin undergoes dephosphorylation, similar to responses observed under dim light exposure, which has been associated with myopia progression in both animal and human studies." (PMID 40736176, 2025). "We identified significant selection signatures in myopia-associated genes related to sunlight, including RHO, TSPAN10, and MED1, and we validated the interaction between these genes and the light environment." (PMID 37919796, 2023). "Retinal pathways found at myopia onset for the occlVopen*time category contrast with those during progression and include the rhodopsin pathway, Krebs cycle pathway and the mitochondrial complex 1 assembly pathway." (PMID 39028695, 2024). "In the overall category, retinal pathways at myopia onset include those involved in rhodopsin function, phototransduction, oxidative metabolism and various structural components." (PMID 39028695, 2024). "Previous studies have pointed out that the expression of rhodopsin has a relatively limited impact on defocus myopia." (PMID 39421610, 2024). "Lastly, previous studies have demonstrated that changes in rhodopsin and arrestin expression are involved in the mechanism of myopia development." (PMID 32318566, 2020). "Through targeted MS analyses, we accurately mapped the phosphorylation sites within the opsin sequences of RHO, OPSV, and OPSB, further validating the critical roles of opsin phosphorylation during myopia and hyperopia development." (PMID 40736176, 2025). "While there may be complex interactions between thyroid dysfunction and pathological myopia, and TTR may serve as a molecular bridge between these conditions, this does not necessarily indicate a direct genetic link, particularly in relation to RHO gene mutations." (PMID 40837568, 2025). "Therefore, selective signatures in RHO and TSPAN10 may result from sunlight-related environmental factors, such as pigmentation, rather than selective pressure on myopia." (PMID 37919796, 2023).
Obesity (7 papers, 2013 to 2024). Accumulation of substantial excess body fat. "RHO was not up-regulated in obesity may be due to the fact that the protein encoded by RHO mainly act on vision in low-light conditions and didn’t play a role in obesity-related pathways." (PMID 35481418, 2022).
colorectal cancer (6 papers, 2017 to 2023). A primary or metastatic malignant neoplasm that affects the colon or rectum. "Three of these genes (Rgs16, Rassf3 and Fam13a) are members of the RAC/RHO/RAS pathway, and dysregulated Rgs16 has been associated with poor prognosis in colorectal cancer." (PMID 28219480, 2017). "Colorectal cancer cells secrete 12(S)-HETE, which promotes CAF retraction from colorectal cancer spheroids by activating myosin light chain 2 (MLC2) through Ca2+/RHO/ROCK signaling axis, facilitating colorectal cancer cell migration into the stroma and surrounding regions." (PMID 34768796, 2021). "Finally, the RHO GEF TIAM1 is another example of the complex function of RHO GTPase regulators in cancer, specifically in colorectal cancer, where it limits the acquisition of migratory properties through the inhibition of the YAP/TAZ pathway." (PMID 34571765, 2021).
age-related macular degeneration (5 papers, 2013 to 2026). Age-related loss of vision in the central portion of the retina (macula), secondary to retinal degeneration. "The non-invasive in vivo optical imaging of rhodopsin activation extends the diagnostic capability of optoretinography, and may facilitate personalized, objective assessment of rod dysfunction and visual cycle impairment in inherited and age-related macular degeneration." (PMID 41495013, 2026). "In this location, they can effectively protect vulnerable polyunsaturated phospholipids and rhodopsin through their antioxidant action, according to the most accepted mechanism through which macular carotenoids, lutein and zeaxanthin, protect the retina from age-related macular degeneration." (PMID 37760086, 2023).
hepatocellular carcinoma (5 papers, 2017 to 2024). A malignant tumor that arises from hepatocytes. "In hepatocellular carcinoma cells, miR151 down-regulated the Rho GDP dissociation inhibitor α (RhoGDIA) coding transcript, and as a result RAC1, CDC42, and RHO were activated and cell migration was promoted." (PMID 37582765, 2023). "Recent studies indicate that RHO GTPases participate in the proliferation, migration, invasion and metastasis of cancer, playing an essential role in the tumorigenesis and progression of hepatocellular carcinoma (HCC)." (PMID 36348464, 2022). "It has been reported that enhanced activity of RHO stimulates the in vitro migration of papillary thyroid cancer (PTC), hepatocellular carcinoma and human colon cancer cells." (PMID 28640862, 2017).
Oguchi disease (5 papers, 2009 to 2026). Oguchi disease is an autosomal recessive retinal disorder characterized by congenital stationary night blindness and the Mizuo-Nakamura phenomenon. "In Oguchi disease, shut-off of light-activated rhodopsin is impaired (due to defective action of rhodopsin kinase, encoded by GRK1, or arrestin, encoded by SAG)." (PMID 34127841, 2021).
diabetic retinopathy (4 papers, 2013 to 2022). "It has been reported that when these anthocyanins are continuously ingested, they show positive effects in the improvement of diabetic vasculopathy, diabetic retinopathy, and visual acuity via rhodopsin resynthesis." (PMID 35784391, 2022). "In a study in individuals with diabetic retinopathy, whole blood mRNA levels of rhodopsin have been shown to reflect a benefit in differentiating the stages of the disease." (PMID 34480211, 2021). "In addition we found ALDH1A1, RBP4, APOB, APOA1, RBP1, APOE and RHO genes enriched in retinoid metabolic process as unique GO in diabetic retinopathy." (PMID 28761062, 2017).
retinal (4 papers, 2008 to 2021). "By combining a P23H-rhodopsin transgene with these normal alleles, we were able to assess the effects of rhodopsin expression on rod cell structure and retinal neurodegeneration." (PMID 23185477, 2012).
sarcoma (4 papers, 2015 to 2023). A usually aggressive malignant neoplasm of the soft tissue or bone. "ROPs (RHO (RAS homologue) of plants, or RACs, for rat sarcoma (RAS)-related C3 botulinum toxin substrate) form a unique subfamily of small monomeric RHO GTPases in plants." (PMID 36562946, 2023). "Plant monomeric RHO GTPases (rat sarcoma homologues, also called RAC for rat sarcoma-related C3 botulinum toxin substrate or ROP for RHO of plants) are involved in immunity and susceptibility to plant diseases." (PMID 27056842, 2016).
Usher syndrome (4 papers, 2017 to 2025). A syndromic diseae characterized by the association of sensorineural deafness (usually congenital) with retinitis pigmentosa and progressive vision loss. "In whirler mouse (Usher syndrome type 2D) photoreceptors, rhodopsin was found to be mislocalized, as were both rhodopsin and blue cone opsin in Myo7a mutant mice (Usher syndrome type 1B) and zebrafish." (PMID 31998945, 2020). "Support for a role of RPGR and gelsolin in ciliary function and rhodopsin trafficking comes from work examining Usher Syndrome, a syndromic form of RP and deafness." (PMID 28814713, 2017).
Alzheimer disease (3 papers, 2012 to 2023). A progressive, neurodegenerative disease characterized by loss of function and death of nerve cells in several areas of the brain leading to loss of cognitive function such as memory and language. "While rhodopsin levels are most closely associated with Alzheimer’s disease, they cannot be used for making a differential diagnosis with other neurodegenerative disorders, e.g., Parkinson’s disease." (PMID 38137479, 2023).
ciliopathies (3 papers, 2020 to 2022). "The past studies indicate that mouse models of ciliopathies caused by Tulp1 and IFT88 mutations manifest rhodopsin mislocalization and accumulation of rhodopsin-laden vesicles, as was observed in this study." (PMID 32376599, 2020).
gastric cancer (3 papers, 2018 to 2024). A primary or metastatic malignant neoplasm involving the stomach. "Given that cell migration/invasion activities are regulated by complex crosstalk between RHO GTPases38–40, further biochemical studies are warranted to explore how CLDN18-ARHGAP26 affect the migration/invasion activities of gastric cancer cells." (PMID 30361512, 2018).
glioblastoma (3 papers, 2018 to 2024). The most malignant astrocytic tumor (WHO grade IV). "In our MB models, increased RHO activity is associated with a more differentiated phenotype, and this is consistent with previous findings in glioblastoma stem cells in which ROCK inhibitor treatment enhanced tumorsphere formation." (PMID 29377567, 2018).
Hypertension (3 papers, 2020 to 2025). The presence of chronic increased pressure in the systemic arterial system. "Other Class I PI3K isoforms may also hold roles in hypertension, with p110δ expression being upregulated in aortas of hypertensive rats, while Class II PI3KC2α appears to regulate vascular smooth muscle contraction and play a role in spontaneous hypertension in rats via a Ca2+-PI3KC2α-RHO axis." (PMID 32002690, 2020).
Leber congenital amaurosis (3 papers, 2015 to 2021). Leber congenital amaurosis (LCA) is a retinal dystrophy defined by blindness and responses to electrophysiological stimulation (Ganzfeld electroretinogram (ERG)) below threshold, associated with severe visual impairment within the first year of life. "Another model is the RPE-specific protein 65 kDA (RPE65) mutant mouse model, which is used to study Leber congenital amaurosis (LCA) and RP since the RPE 65 defect leads to a faulty isomerase which can no longer convert the chromophore necessary for rhodopsin to detect light." (PMID 26239347, 2015).